CSRP1 (cysteine and glycine rich protein 1)
Description:
Could play a role in neuronal development.
Synonyms: CRP; CRP1; HEL-141; CSRP; CYRP; D1S181E; HEL-S-286
Tractability: PROTAC: UniProt records ubiquitination sites on it; ubiquitination databases record sites on it; its protein half-life has been measured.
Gene: Protein-coding gene on chromosome 1 (201,483,530 to 201,513,100, reverse strand). Ensembl gene ENSG00000159176.
Subcellular location: Nucleus
Pathways (Reactome):
Cellular responses to stimuli: MTF1 activates gene expression
Gene Ontology:
Molecular function: protein binding; RNA binding; actinin binding; structural constituent of muscle; zinc ion binding
Biological process: platelet aggregation; muscle tissue development; sarcomere organization
Cellular component: extracellular exosome; focal adhesion; nucleus; cytoplasm; Z disc
Genetic constraint (gnomAD): Loss-of-function variants: 16 observed, 26.58 expected, observed/expected ratio (o/e) 0.6, 90% interval 0.41 to 0.91. The upper end of that interval is the gene's LOEUF score, 0.91, which puts it in group 3 of 6, group 1 being the genes least tolerant of losing a copy. Missense variants: 211 observed, 255.72 expected, observed/expected ratio (o/e) 0.83, 90% interval 0.74 to 0.93. Synonymous variants: 97 observed, 100.87 expected, observed/expected ratio (o/e) 0.96, 90% interval 0.81 to 1.14.
Gene-disease validity (ClinGen):
ClinGen rates the evidence that CSRP1 causes each of these diseases.
congenital heart disease (autosomal dominant): Disputed. A heart disease that is present at birth.
Homologues: Orthologues: chimpanzee CSRP1 (100% identical), guinea pig CSRP1 (99% identical), mouse Csrp1 (99% identical), rabbit CSRP1 (98% identical), pig CSRP1 (97% identical), rat Csrp1 (96% identical), macaque CSRP1 (91% identical), dog CSRP1 (83% identical), zebrafish csrp1a (83% identical), zebrafish csrp1b (82% identical), tropical clawed frog csrp1 (81% identical), Drosophila melanogaster Mlp60A (51% identical), and 2 more. Paralogues in human: CSRP2 (79% identical), CSRP3 (67% identical).
Diseases named in the same sentence as CSRP1 in open-access papers:
CSRP1 is named in the same sentence as 34 diseases in open-access papers, as found by Europe PMC text mining. Sharing a sentence is not in itself a finding about the gene and the disease. The quoted sentences say what the papers report.
acute myeloid leukemia (4 papers, 2023 to 2024). Acute myeloid leukemia (AML) is a group of neoplasms arising from precursor cells committed to the myeloid cell-line differentiation. "CSRP1 was included in a gene signature that identified a high-risk subgroup of acute myeloid leukemia with worse prognosis." (PMID 38813484, 2023). "Additionally, there is an observed association between CSRP1 and DNA methylation in acute myeloid leukemia." (PMID 38937285, 2024). "Consistently, higher expression of CSRP1 helps identify a high-risk subgroup of acute myeloid leukemia (AML) with worse prognosis." (PMID 37113556, 2023). "Despite its recognition as a potential prognostic factor and therapeutic target in various cancers, the specific link between CSRP1 and acute myeloid leukemia remains unexplored." (PMID 38937285, 2024). "Abnormal expression of CSRP1 was reported within several malignancies such as prostate cancer and acute myeloid leukemia." (PMID 37113556, 2023). "By comparing the expression of CSRP1 in normal samples in the GTEX database and corresponding tumor samples in the TCGA database, CSRP1 was found to be significantly overexpressed in 7 cancers, including acute myeloid leukemia (LAML), and underexpressed in 18 cancers." (PMID 38546813, 2024).
hepatocellular carcinoma (4 papers, 2008 to 2024). A malignant tumor that arises from hepatocytes. "Hepatocellular carcinoma (HCC) causes abnormal methylation to inactivate CSRP1, which may be a key biomarker for cancer." (PMID 38546813, 2024). "On one hand, decreased CSRP1 protein expression was observed in hepatocellular carcinoma (HCC), indicating its role as an anticancer factor." (PMID 37113556, 2023). "Hirasawa and collaborators (2006) suggest the use of CSRP as an important biomarker of hepatocellular carcinoma malignancy, because CSRP1 is inactivated in this model by aberrant methylation." (PMID 19055846, 2008). "In hepatocellular carcinoma (HCC), 56% of cases had aberrant methylation and a lower expression of CSRP1 compared to normal liver tissue." (PMID 38813484, 2023).
prostate carcinoma (4 papers, 2008 to 2025). A carcinoma that arises from epithelial cells of the prostate gland. "In contrast, in prostate cancer, it was reported that a high expression of CSRP1 was associated with longer DFS." (PMID 38813484, 2023). "Moreover, high CSRP1 expression was associated with longer disease-free survival (DFS) in prostate cancer." (PMID 38813484, 2023). "Studies have shown that CSRP1 is closely related to adrenocortical carcinoma, the progression from prostate hyperplasia to prostate cancer, bladder cancer, and kidney renal papillary cell carcinoma." (PMID 39994616, 2025). "CSRP1 was listed among hub genes that are downregulated in prostate cancer compared to benign prostate hyperplasia." (PMID 38813484, 2023). "This hypothesis was substantiated through experiments using PC3 and LNCaP prostate cancer cells, where we conducted scratch assays and apoptosis assays, all of which confirmed CSRP1’s role in suppressing tumor growth." (PMID 39994616, 2025). "The IHC analysis revealed a close correlation between CSRP1 expression levels and the development of CRPC, thus consolidating our hypothesis that CSRP1 plays a critical role in prostate cancer progression." (PMID 39994616, 2025). "Similarly, CSPR1 is decreased in prostate cancer tissues compared to that in normal prostate tissues, and lower CSRP1 can predict a better disease-free survival of prostate cancer." (PMID 37113556, 2023). "Given that the progression of HSPC has been previously tied to invasion-related genes like intercellular cell adhesion molecule-1, it is plausible that CSRP1 may modulate the invasive capacity of prostate cancer cells, thereby influencing the transition from HSPC to CRPC." (PMID 39994616, 2025). "The MYLK, KLK2, KLK3, HAN11, LTF, CSRP1 and TGM4 genes presented significant changes in their functional connectivity between normal and tumoral conditions and were also classified as the top seven most informative genes for the prostate cancer genesis process by our discriminant analysis." (PMID 19055846, 2008).
colon cancer (3 papers, 2017 to 2023). "Overall, these data revealed that the CSRP1 expression was correlated with the mesenchymal gene expression, suggesting an association with relatively mesenchymal subtypes of colon cancer." (PMID 38813484, 2023). "A recent study showed that the knockdown of CSRP1 in colon cancer cell lines caused a reduction in cell proliferation and migration." (PMID 38813484, 2023). "In short, the CSRP1 expression was associated with a more mesenchymal, stroma-rich molecular profile and poor prognosis in colon cancer." (PMID 38813484, 2023). "In this study, the aim was to assess the biological and clinical parameters that are associated with CSRP1 expression in colon cancer." (PMID 38813484, 2023). "Based on the in silico findings from TCGA datasets, we were engaged to further explore clinical meaning of CSRP1 protein in colon cancer." (PMID 37113556, 2023). "CSRP1 expression is associated with CMS4, a more mesenchymal stroma-rich molecular profile, and poor prognosis in colon cancer." (PMID 38813484, 2023). "In silico analyses of bulk transcriptomic data from colon tumors showed that tumors with a high CSRP1 expression had a stroma-rich molecular profile that overlapped, to a large extent, with a CMS4 phenotype." (PMID 38813484, 2023). "In colon cancer, CSRP1 has been listed in a 3-gene list generated to distinguish colon cancer from normal colon tissue with 90.32% accuracy." (PMID 38813484, 2023). "As an example, IG-SVM achieved a classification accuracy of 90.32% for colon cancer, which is difficult to be accurately classified, only based on three genes including CSRP1, MYL9, and GUCA2B." (PMID 29246519, 2017). "Lower CSRP1 expression was noted in colon tumors compared to normal colon tissue." (PMID 38813484, 2023). "CMS4 colon tumors had a significantly higher CSRP1 expression compared to other CMSs." (PMID 38813484, 2023). "With further large-scale validation, the CSRP1 gene might be shown to have the potential to contribute to patient stratification in colon cancer." (PMID 38813484, 2023). "In HCC, the CSRP1 expression was suppressed via promoter methylation, and, in line with that, the data herein showed a significant negative correlation between RNAseq-based expression and the methylation of the CSRP1 gene in colon cancer." (PMID 38813484, 2023). "Furthermore, the CSRP1 expression and methylation levels were negatively correlated in colon tumors." (PMID 38813484, 2023). "The findings herein showed that the CSRP1 expression was downregulated in colon cancer compared to normal colon tissue." (PMID 38813484, 2023).
bladder cancer (2 papers, 2022 to 2023). "A previous study, which found differential expression of the SYNM, TPM1, CSRP1 gene in bladder cancer, demonstrated the reliability of our study." (PMID 34541834, 2022).
cholangiocarcinoma (2 papers, 2023 to 2025). A carcinoma that arises from the intrahepatic biliary tree (intrahepatic cholangiocarcinoma) or from the junction, or adjacent to the junction, of the right and left hepatic ducts (hilar cholangiocarcinoma). "RiskScore of cholangiocarcinoma patients with 10 genes calculated followed the formula: The RiskScore=0.429*VEGFC -0.434*NFKBIA-0.884*NLRX1+0.54*AKT1+0.629*CSRP1+0.406*EPO+0.833*IL31RA+1.023*LEP+0.341*MUC4+0.363*SEMA4B." (PMID 36817485, 2023). "Notably, CSRP1 has been recognized as a tumor suppressor in several types of cancers including colorectal cancer, and cholangiocarcinoma." (PMID 39994616, 2025).
colon adenocarcinoma (2 papers, 2023). "A recent study showed that a high expression of CSRP1 was associated with poor prognosis in The Cancer Genome Atlas (TCGA) colon adenocarcinoma (COAD) cohort." (PMID 38813484, 2023). "The methylation level of the CSRP1 gene was negatively correlated (r = −0.57, p < 0.0001) with CSRP1 expression in The Cancer Genome Atlas colon adenocarcinoma dataset." (PMID 38813484, 2023). "Here, we explored function of CSRP1 within colon adenocarcinoma (COAD) for the first time." (PMID 37113556, 2023). "A previous study also suggested the dysregulated expression of CSRP1 in colon adenocarcinoma (COAD), however, the study did not further investigate its clinical significance or functional mechanisms." (PMID 37113556, 2023).
glioma (2 papers, 2022 to 2025). A benign or malignant brain and spinal cord tumor that arises from glial cells (astrocytes, oligodendrocytes, ependymal cells). "In the Glioma/NC group, 8 proteins (COL1A1, PRL, VWF, HBD, SF3B1, NME3, RRBP1, and CSRP1) were selected, with an AUC of 0.892 in the training set and 0.871 in the validation set (accuracy: 78.5%)." (PMID 39716938, 2025).
adenoma (1 paper, 2024). A neoplasm arising from the epithelium. "Most over-represented proteins in the adenoma cell line ZMTH3 were associated with RNA-binding and protein expression (EIF1AX, CSRP1, PPIC), suggesting enhanced protein biosynthesis activity." (PMID 39462388, 2024).
adrenocortical carcinoma (1 paper, 2024). "CSRP1 is associated with poor clinicopathological features in adrenocortical carcinoma (ACC)." (PMID 38546813, 2024).
atherosclerosis (1 paper, 2025). A disease characterized by the build-up of fatty material and calcium deposition in the arterial wall resulting in partial or complete occlusion of the arterial lumen. "We identified 12 lactylation-related genes that are more reliably associated with atherosclerosis: five upregulated genes (LSP1, IKZF1, MNDA, RCC2, and WAS) and seven downregulated genes (CSRP2, PPP1CB, CSRP1, HEXIM1, CALD1, PDLIM1, and RANBP2)." (PMID 40248193, 2025).
breast carcinoma (1 paper, 2024). "Interestingly, the RNA-binding protein CSRP1 was one of the most abundant proteins for all CMTs, which has been linked to human breast cancer for its role in alteration of gene regulation, cell growth and differentiation." (PMID 39462388, 2024).
cerebral palsy (1 paper, 2025). A group of disorders affecting the development of movement and posture, often accompanied by disturbances of sensation, perception, cognition, and behavior. "A study indicated methylation of CSRP1 and USP44 genes in patients diagnosed with cerebral palsy born preterm compared with those born preterm without cerebral palsy." (PMID 39906903, 2025).
colorectal tumors (1 paper, 2023). "Analysis of the scRNAseq data revealed that CSRP1 was expressed by epithelial cells and cancer-associated fibroblasts in the colorectal tumor microenvironment, which was also confirmed by the protein expression data from the Human Protein Atlas database." (PMID 38813484, 2023). "CSRP1 expression was downregulated in 15 of 19 colorectal tumors; thus, it was suggested as a potential tumor suppressor in colorectal cancer (CRC)." (PMID 38813484, 2023). "In order to identify the cell types that express CSRP1, a scRNAseq dataset (GSE178318) of colorectal tumors was analyzed." (PMID 38813484, 2023).
gastric cancer (1 paper, 2023). A primary or metastatic malignant neoplasm involving the stomach. "Interestingly, it has been reported that celecoxib treatment induced an upregulated CSRP1 in gastric cancer cells, highlighting its crosstalk with antitumor drugs." (PMID 37113556, 2023).
Holt-Oram syndrome (1 paper, 2017). Holt-Oram syndrome (HOS) is the most common form of heart-hand syndrome and is characterized by skeletal abnormalities of the upper limbs and mild-to-severe congenital cardiac defects. "Additionally, we documented a novel interaction of CSRP1 with TBX5, a member of the T-box family, implicated in the Holt-Oram syndrome." (PMID 29326753, 2017).
idiopathic pulmonary fibrosis (1 paper, 2023). Idiopathic pulmonary fibrosis (IPF) is a nonneoplastic pulmonary disease that is characterized by the formation of scar tissue within the lungs in the absence of any known cause. "Furthermore, the CSRP1 expression was significantly higher in idiopathic pulmonary fibrosis compared to control lung tissue." (PMID 38813484, 2023).
infarction (1 paper, 2024). A localised pathological necrosis of tissue resulting from obstruction of the blood supply usually by a thrombus, an embolus, or vascular torsion. "In contrast, the downregulation of proteins such as ACTN1, MYL9, CSRP1, COMP, and PI16, which are closely associated with muscle cell development and contractility, suggests a disruption in muscular and structural integrity within the heart in the acute phase post-infarction." (PMID 39513871, 2024).
lung fibrosis (1 paper, 2023). "Higher CSRP1 expression was also reported in lung fibrosis compared to control lung tissue." (PMID 38813484, 2023).
pancreatic cancer (1 paper, 2023). "While little is known about CSRP1 in pancreatic cancer, S100A16 has been extensively studied in PDAC." (PMID 36983764, 2023).
prostate adenocarcinoma (1 paper, 2025). "At the same time, we found through The Cancer Genome Atlas Prostate Adenocarcinoma (TCGA-PRAD) database demonstrated that the disease free survival of the Low CSRP1 group was worse than that of the High CSRP1 group." (PMID 39994616, 2025).
prostate tumors (1 paper, 2025). "In TCGA, the expression of CSRP1 in prostate tumor tissues was significantly lower than that in normal tissues." (PMID 39994616, 2025). "The results indicate that CSRP1 played anti-oncogene roles in PCa, suppressed the formation and growth of prostate tumors, and promoted their androgen dependence." (PMID 39994616, 2025).
rectal tumors (1 paper, 2023). "When the expression of CSRP1 was analyzed via the GEPIA web tool, a significantly lower expression of CSRP1 was noted in both colon and rectal tumors (TCGA) compared to normal colon and rectum tissue (TCGA+GTEx) (log fold change >3, p < 0.05)." (PMID 38813484, 2023).
syphilis (1 paper, 2025). A contagious bacterial infection caused by the spirochete Treponema pallidum. "This study reveals a novel RNA splicing‐mediated dissemination mechanism, proposing CSRP1/MYO10 as therapeutic targets to limit bacterial dissemination in syphilis." (PMID 40666038, 2025).
type 2 diabetes (1 paper, 2016). "For example, microarray studies performed on human pancreatic islets isolated from patients with type 2 diabetes and glucose-tolerant controls identified, among other changes, overexpression of ENPP1, TSPAN4, TSPAN8, CSRP1, REG3A and REG3G, genes that were also upregulated with age in our study." (PMID 26699651, 2016).